HP (haptoglobin)
Diseases named in the same sentence as HP in open-access papers (continued):
Sharing a sentence is not in itself a finding about the gene and the disease.
Pleuritis (1 paper, 2017). Inflammation of the pleura. "The LSC pigs had higher haptoglobin concentrations in blood and higher pleuritis scores for lungs at slaughter than HSC pigs, confirming a difference in health status." (PMID 28481880, 2017).
polyarthritis (1 paper, 2022). "Haptoglobin showed in general the highest correlation to cJADAS27, with r = 0.339, p < 0.001 overall, r = 0.415, p < 0.001 for polyarthritis, and r = 0.472, p < 0.001 for persistent oligoarthritis." (PMID 35964131, 2022).
polyarticular JIA (1 paper, 2022). "Levels of haptoglobin were markedly elevated in both systemic JIA and polyarticular JIA, with the former demonstrating the greatest overall expression." (PMID 35964131, 2022).
polycystic ovary syndrome (1 paper, 2009). A disorder that manifests as multiple cysts on the ovaries. "The association of polycystic ovary syndrome with Hp2 alleles suggests that the anti-oxidant and anti-inflammatory properties of haptoglobin may be reduced in these patients." (PMID 19440331, 2009). "Serum haptoglobin and the haptoglobin α–chain polymorphism were determined in 141 patients with polycystic ovary syndrome and 102 non-hyperandrogenic women." (PMID 19440331, 2009).
porphyria (1 paper, 2025). Porphyria is a group of diseases in which substances called porphyrins build up, negatively affecting the skin or nervous system. "However, considering the etiology of the pathology (hemolytic disorders, parasite invasion, gastric problems, or porphyria treatment), the plasma scavenging system (haptoglobin, hemopexin, and albumin) would be challenged either by the overwhelming formation of hemin and hematin." (PMID 39996728, 2025).
pregnancy toxemia (1 paper, 2025). "In our study, serum haptoglobin concentration was found to increase significantly in the presence of pregnancy toxemia, consistent with previous studies." (PMID 40492724, 2025).
pyelonephritis (1 paper, 2013). An inflammatory process affecting the kidney. "It is not standard of care at our institution to draw lactose dehydrogenase (LDH) or haptoglobin for patients with pyelonephritis." (PMID 24369448, 2013).
rhabdomyolysis (1 paper, 2025). Necrosis or disintegration of skeletal muscle often followed by myoglobinuria. "If liver‐related causes are ruled out, extrahepatic causes like rhabdomyolysis and hemolysis should also be evaluated through tests such as myoglobinuria detection, peripheral blood smear examination, and serum haptoglobin measurement." (PMID 40552755, 2025).
rheumatic diseases (1 paper, 2014). "In the pathogenesis of rheumatic diseases are also implicated the altered glycosylation of other than IgG plasma proteins such as fibronectin, transferrin, α1-acid glycoprotein and haptoglobin." (PMID 24346772, 2014). "The increased concentration of TSA in rheumatic diseases can concern the increased level of sialylated glycoproteins such as α1-acid glycoprotein, haptoglobin and α1-antitrypsin." (PMID 24346772, 2014). "All acute-phase proteins in patients with rheumatic diseases were significantly changed in comparison with the controls: positive acute-phase proteins (CRP, AGP, HP and AAT) were elevated and the negative (TRF)—decreased." (PMID 24346772, 2014).
rubella (1 paper, 2018). A viral infection caused by the rubella virus. "Additionally, we found a significant quadratic term for five out of the 15 serologies, highlighting that the rate of change in probability of seropositivity with respect to age is higher for rubella and lower for HSV-1, HP, HBs, and EBV EBNA in older people as compared to younger donors." (PMID 30053915, 2018).
severe acute respiratory syndrome (1 paper, 2011). A viral respiratory infection caused by the SARS coronavirus. "Haptoglobin isoforms and fragments are also elevated in plasma of severe acute respiratory syndrome (SARS) patients." (PMID 21906349, 2011).
sleeping sickness (1 paper, 2017). "An association between one SNP in HP and the susceptibility to HAT was revealed in inhabitants of sleeping sickness foci of Cameroon." (PMID 29077717, 2017).
spondyloarthropathy (1 paper, 2021). A group of inflammatory rheumatic diseases associated with arthritis and enthesitis, and often involving the axial skeleton. "Returning to the topic of our work—haptoglobin and its related protein, zonulin—what is their role in spondyloarthropathy?—currently, we are not able to answer this question unequivocally on the basis of the available literature." (PMID 33800376, 2021).
staphylococcus aureus pneumonia (1 paper, 2020). An pneumonia caused by infection with Staphylococcus aureus. "Another animal study infused commercial human haptoglobin into dog models of Staphylococcus aureus pneumonia, and found that treated dogs had increased clearance of cell‐free hemoglobin with lower circulating iron, less injury, and increased survival." (PMID 32596989, 2020).
thyroid (1 paper, 2012). "The concurrent absent or low expression levels of haptoglobin, ferritin light chain, and ferritin heavy chain in Riedel's thyroiditis fine-needle aspiration samples strongly indicate the benign nature of the thyroid lesion." (PMID 22480342, 2012).
Tremor (1 paper, 2019). An unintentional, oscillating to-and-fro muscle movement about a joint axis. "For example, it has been reported that plasma transferrin level correlates with the tremor-dominant phenotype of Parkinson’s disease, as well as the abnormally low iron in PD patients was especially pronounced for subjects of haptoglobin Hp 2-1 phenotype, which also have higher risk of PD." (PMID 31616238, 2019).
urticaria (1 paper, 2026). A vascular reaction of the skin characterized by erythema and wheal formation due to localized increase of vascular permeability. "Patients who achieved complete urticaria control had higher baseline HP levels than those exhibiting incomplete control, and the reductions in HP levels after treatment paralleled improvements in the UAS7 and UCT score." (PMID 41498512, 2026). "ROC analysis indicated that a baseline HP level ≥ 1249 μg/mL may help identify patients more likely to achieve complete urticaria control (AUC = 0.69, 95% CI = 0.55–0.83; sensitivity, 65.2%; specificity, 74.4%; p = 0.007)." (PMID 41498512, 2026). "Notably, a baseline HP level ≥ 1249 μg/mL independently predicted complete urticaria control." (PMID 41498512, 2026).
uterine disease (1 paper, 2017). "This temporal pattern observed for haptoglobin levels is similar to that in cows with uterine disease." (PMID 28542500, 2017).
vasculitis (1 paper, 2020). "Inflammatory molecules of haptoglobin (HP), C-Type Lectin Domain Family 4 Member D (CLEC4D), and G-protein coupled receptor 84 (GPR84) are glycoproteins involved in cardiovascular disease and vasculitis." (PMID 33344384, 2020).
viral meningitis (1 paper, 2015). Inflammation of the membranes surrounding the brain and spinal cord due to a viral infection. "These authors proposed six proteins as candidate markers for the differential diagnosis of bacterial and viral meningitis, three of them were also identified in the present study (haptoglobin, fibrinogen β chain and prostaglandin D synthase)." (PMID 26040285, 2015).
vitamin C deficiency (1 paper, 2012). "The Hp1 and Hp2 polymorphisms in the hemoglobin-binding protein haptoglobin (Hp) were also studied in vitamin C deficiency." (PMID 22536488, 2012).
vitiligo (1 paper, 2024). Generalized well circumscribed patches of leukoderma that are generally distributed over symmetric body locations and is due to autoimmune destruction of melanocytes. "The differential expression of haptoglobin and haptoglobin-related protein in vitiligo may be linked to their roles in tissue protection and prevention of oxidative damage." (PMID 38715599, 2024).
Zinc deficiency (1 paper, 2024). A deficiency of the essential metal Zinc; an essential cofactor for many enzymes. "Currently, the clinical activators of the HP gene mainly consist of zinc supplements, such as zinc chloride and zinc sulfate, for treating zinc deficiency and parenteral nutrition." (PMID 38644354, 2024).
infection (214 papers, 2006 to 2026). The state of being infected such as from the introduction of a foreign agent such as serum, vaccine, antigenic substance or organism. "Next, to evaluate a connection between host immune system activation and survival, we normalized protein abundance for infection-associated host proteins and observed a substantial increase in lipocalin-2, cathepsin G, and haptoglobin at 4 dpi for mouse #6." (PMID 41061967, 2025). "Haptoglobin, an acute-phase protein encoded by the HP gene, is primarily synthesized by the liver and released into the bloodstream in response to inflammation, infection, or tissue damage." (PMID 39710434, 2024). "Vaccination, similarly to infection, is associated with elevated levels of haptoglobin, cortisol, TNF-a, insulin, leptin, ceruloplasmin, and fibrinogen." (PMID 38662753, 2024). "In this study, Staphylococci play role in causing infection and increasing the concentration of haptoglobin as an indicator of inflammation." (PMID 33665459, 2021). "So far, only subtypes H5 and H7 AI viruses have been observed to acquire HP mutations under natural circumstances, and infection of poultry with these viruses are therefore considered to be notifiable regardless of their particular pathogenicity." (PMID 30514922, 2018). "Mice deficient in haemopexin displayed higher median levels of haptoglobin at baseline prior to infection (89 ug/mL compared to undetectable) compared to their wild-type counterparts." (PMID 26691827, 2015). "In response to acute haemolysis, haemopexin-deficient mice increase their plasma levels of haptoglobin to a greater degree than their heterozygous or wild-type littermates throughout the course of infection (p = 0.0002)." (PMID 26691827, 2015). "Acute increases in haptoglobin concentrations normally signify an infection-associated inflammation." (PMID 22562421, 2012). "Additionally, NTHi strains deficient in the ability to acquire haemoglobin-haptoglobin have an attenuated ability to cause infection." (PMID 40444152, 2025). "We validated detection of haptoglobin, an immune-associated protein involved in host oxidative homeostasis, opsonization, and hemoglobin scavenging upon host cell proteolysis, through Western blot in whole blood samples across time and infection state." (PMID 41061967, 2025). "Additionally, we correlated activation of haptoglobin by the host in response to proteolysis-associated proteins produced by C. neoformans throughout infection." (PMID 41061967, 2025). "Other authors published that haptoglobin concentrations greater than 20 mg/dL are associated with mild infection and above 40 mg/dL could be associated with severe infection." (PMID 38997979, 2024). "Moreover, as an acute phase protein, HP is dynamically upregulated several fold by stress-associated stimuli including infection." (PMID 39416789, 2024). "Higher haptoglobin concentrations are associated with tissue injury, inflammation or infection." (PMID 33592073, 2021). "infection was only associated with a 1.4-fold increase in serum haptoglobin concentrations." (PMID 32555669, 2020). "Indeed, we found that the highest and lowest levels of haptoglobin and the neutrophil to lymphocyte ratio were associated with infection or infestation." (PMID 31766647, 2019). "We found that the plasma concentration of haptoglobin was strongly associated with the infection status and could predict probabilities of survival." (PMID 28070333, 2017). "We speculated that serum haptoglobin levels might be reflected seriousness of infection, which could be caused by tumor necrosis or metastasis." (PMID 27248178, 2016). "Higher levels of circulating haptoglobin in birds from native populations might result from a stronger innate immunity or from an ongoing reaction to infections due to a higher parasitic risk than in non‐native birds." (PMID 28725417, 2016).
infection (continued). "Haptoglobin (Hp), encoded by the gene HP, is an abundant acute-phase glycoprotein in the plasma which binds free haemoglobin (Hb) that has been released by lysis of erythrocytes, often as a result of infection." (PMID 24005574, 2014). "By contrast infection caused haptoglobin concentrations to rise to between approximately 500 to 2500 μg/ml at Day 5 post infection, which was a significant (P < 0.05) increase for all infected groups with the exception of the control group in study C, where only a trend was observed (P = 0.112)." (PMID 19948011, 2009). "It is also possible that the HP expression pattern differ between the two species, with B. cinerea HPs being predominantly expressed during sexual development, while S. sclerotiorum HPs might be more tightly associated with infection-related processes." (PMID 41305368, 2025). "It is difficult to speculate why mean haptoglobin levels were variable in these patients while other biological markers of hemolysis improved; however, haptoglobin levels can vary with infection, inflammation, genetic polymorphisms, and, in some cases, blood transfusions." (PMID 35869170, 2022). "Additionally, we also measured serum HP antibody and pepsinogen levels, which directly reflect current/former chronic inflammation of the gastric mucosa due to infection, and investigated their association with global methylation levels with and without adjustment by CRP concentration." (PMID 29439678, 2018). "Haptoglobin is an acidoglycoprotein that is highly expressed in blood and is believed to act as a cytokine following release from activated macrophages during the initial stages of pathogenic infection and tissue damage, which can stimulate the liver to produce acute phase reactive protein." (PMID 28116073, 2017). "Further studies should correlate CRP kinetics with other inflammatory markers (e.g., pro-inflammatory cytokines, haptoglobin) and relevant clinical outcomes, such as surgical site infection or implant failure." (PMID 41472138, 2025). "Haptoglobin is an acute-phase glycoprotein that is released into the bloodstream in response to tissue injury such as trauma or infection, having an important interaction with haemoglobin." (PMID 39943212, 2025). "In the early stages of disease infection, the concentration of Hp can increase dramatically even before viremia, this makes HP a characteristic marker of early infection." (PMID 41305467, 2025). "These proteins include C-reactive protein (CRP), serum amyloid A (SAA), and haptoglobin (Hp); these increase dramatically during acute inflammation, so these proteins are common indicators of inflammation, infection, or tissue damage." (PMID 40943382, 2025). "Haptoglobin is a major acute-phase protein in cattle and has been shown to increase in response to infection, inflammation, or trauma." (PMID 40218414, 2025). "It is also well established that haptoglobin, as an acute-phase protein, increases significantly in response to inflammation and infection in the mammary gland, serving as a reliable indicator of udder health." (PMID 40075958, 2025). "Haptoglobin (HP), another acute-phase reactant, plays a vital role in the body’s response to infection, tissue damage repair, and maintaining internal homeostasis." (PMID 39766283, 2024). "The importance of these results lies in the validation of TFF1, GSTA5, HSPA6, FOS, MPIG6B, F2 and HP not only as key markers for the presence of infection but also for their specificity in differentiating between various Mpox strains." (PMID 39456924, 2024). "A more rapid increase and earlier peak of SAA compared with haptoglobin was also reported in experimental studies in cows after endotoxin challenge and in calves following infection with Mannheimia haemolytica." (PMID 38962710, 2024). "SAA and HP are two major acute-phase proteins in cattle, and their concentrations increase when animals experience stress such as inflammation and infection." (PMID 37630463, 2023).
infection (continued). "Haptoglobin is a major acute phase protein in pigs and an increase in its plasma concentration is an indicator of inflammation and/or infection." (PMID 36717823, 2023). "Together, these results are consistent with previous studies showing that Gps infection enhances HP-PRRSV2 replication." (PMID 37235448, 2023). "Using specific immunoassays, elevated STNC, haptoglobin, and Cath 2 were validated as infection-induced biomarkers in both lines." (PMID 37928534, 2023). "For example, variation in haptoglobin concentration, our index of immune response to a mimicked bacterial infection has numerous functions, including resistance and tolerance to infection." (PMID 36353782, 2023). "Eleven bacterial sequences were correlated with haptoglobin concentration and nine were found to be potential predictors of the strength of the immune response, and implicit of infection severity, notably Weissella and Escherichia." (PMID 37114064, 2023). "The possible mechanistic roles of FCGR3A and haptoglobin in maternal circulation as pathophysiological links with inflammation/infection in the amniotic cavity warrant further investigation." (PMID 37024561, 2023). "Host heme-scavenging proteins were upregulated in both genetic lines during infection including haptoglobin, hepcidin, cathelicidin-1, and heme-binding protein 2-like protein." (PMID 37928534, 2023). "The induction of the innate immune response of gastric epithelial cells and myeloid cells by HP effectors plays a critical role in the outcome of the infection." (PMID 37144125, 2023). "Haptoglobin and pigMAP belong to a group of APPs that react to stimuli (e.g., transportation, stress, infection, and inflammation) with an increase in the blood." (PMID 35892630, 2022). "In the current study, pigs supplemented with antibiotics had reductions in neutrophils and serum concentrations of C-reactive protein and haptoglobin during the peak infection period." (PMID 35016715, 2022). "Concerning CD163, an increase in its expression was observed on D5 compared to D3 in both monocyte subpopulations found in the spleen, suggesting increased removal of hemoglobin/haptoglobin complexes at this point during infection." (PMID 36310859, 2022). "Haptoglobin is a marker of inflammation, its level increasing during infections, injuries, and malignancies." (PMID 35327501, 2022). "As an example, haptoglobin levels increased 27-, 4-, and 9-fold on days 5, 14, and 21 post-infection compared to pre-infection levels." (PMID 36546919, 2022). "Haptoglobin concentrations were increased from 8 to 12 days post-infection (dpi) in all infected groups." (PMID 34551803, 2021). "Haptoglobin is one of several acute phase proteins (APP) released in response to infection, inflammation and stress, and has been shown to increase in pigs after weaning." (PMID 34070802, 2021). "Serum haptoglobin concentrations increased in some individual animals on days 7 and 10 after infection." (PMID 34673945, 2021). "Another mechanism includes release of haptoglobin, an acute-phase protein that is released from the liver during infection." (PMID 34491450, 2021). "In contrast, both groups upregulated expression of haptoglobin in the liver on day 10 after infection (P = 0.01)." (PMID 34673945, 2021). "This is confirmed by a fast and significant increase in haptoglobin levels subsequent to sheep`s infection with Corynebacterium pseudotuberculosis." (PMID 34103567, 2021). "The release of haptoglobin is regulated by the liver, and often activated by cytokines of the interleukin 1 family during the onset of infection." (PMID 33329501, 2020). "Haptoglobin (Hp) is one of the most abundant APPs, second only to albumin and immunoglobins, and its serum levels can be upregulated up to 8-fold in response to infection." (PMID 32694142, 2020).